ARHGEF10 (Rho guanine nucleotide exchange factor 10)
Description:
May play a role in developmental myelination of peripheral nerves.
Synonyms: KIAA0294; Gef10; SNCV
Tractability: PROTAC: ubiquitination databases record sites on it.
Gene: Protein-coding gene on chromosome 8 (1,823,332 to 1,958,642, forward strand). Ensembl gene ENSG00000104728.
Subcellular location (Human Protein Atlas): Nucleoplasm
Pathways (Reactome):
Signal Transduction: CDC42 GTPase cycle; G alpha (12/13) signalling events; NRAGE signals death through JNK; RAC1 GTPase cycle; RHOA GTPase cycle; RHOB GTPase cycle; RHOC GTPase cycle
Gene Ontology:
Molecular function: guanyl-nucleotide exchange factor activity; kinesin binding; protein binding
Biological process: centrosome duplication; mitotic spindle assembly; myelination in peripheral nervous system; positive regulation of Rho protein signal transduction; positive regulation of stress fiber assembly; actin cytoskeleton organization; regulation of small GTPase mediated signal transduction
Cellular component: centrosome; cytoplasm; cytosol
Genetic constraint (gnomAD): Loss-of-function variants: 139 observed, 150.6 expected, observed/expected ratio (o/e) 0.92, 90% interval 0.8 to 1.06. The synonymous counts are far from expectation, so gnomAD's model fits this gene poorly and the ratio says little. Missense variants: 2,183 observed, 1,787.1 expected, observed/expected ratio (o/e) 1.22, 90% interval 1.18 to 1.26. Synonymous variants: 892 observed, 712.4 expected, observed/expected ratio (o/e) 1.25, 90% interval 1.18 to 1.32.
Gene-disease validity (ClinGen):
ClinGen rates the evidence that ARHGEF10 causes each of these diseases.
autosomal dominant slowed nerve conduction velocity (autosomal dominant): Limited.
Homologues: Orthologues: chimpanzee ARHGEF10 (99% identical), macaque ARHGEF10 (97% identical), mouse Arhgef10 (80% identical), rat Arhgef10 (80% identical), dog ARHGEF10 (77% identical), tropical clawed frog arhgef10 (68% identical), pig ARHGEF10 (60% identical), guinea pig ARHGEF10 (57% identical), zebrafish arhgef10 (52% identical), Drosophila melanogaster CG43658 (22% identical). Paralogues in human: ARHGEF10L (41% identical), ARHGEF17 (21% identical).
Diseases named in the same sentence as ARHGEF10 in open-access papers:
ARHGEF10 is named in the same sentence as 42 diseases in open-access papers, as found by Europe PMC text mining. Sharing a sentence is not in itself a finding about the gene and the disease. The quoted sentences say what the papers report.
polyneuropathy (4 papers, 2014 to 2020). A disease or disorder affecting more than one nerve. "In comparison, the age of onset of clinical signs in the previously characterized ARHGEF10-associated polyneuropathy was seen in Leonbergers and Saint Bernards with average ages of 2.2 and 1.6 years, respectively." (PMID 33261176, 2020). "This is the first documented severe polyneuropathy associated with a mutation in ARHGEF10 in any species." (PMID 25275565, 2014). "This first-documented severe polyneuropathy associated with an ARHGEF10 mutation in any species provides an opportunity to gain further insights into the pathobiology of diseases associated with this gene." (PMID 25275565, 2014). "More recently, genetic variants in ARHGEF10 and GJA9 were shown to cause polyneuropathy in Leonbergers, which includes LP as a clinical sign." (PMID 31647804, 2019). "The ARHGEF10 mutation does not, however, by itself account for all cases of polyneuropathy in Leonbergers or Saint Bernards." (PMID 25275565, 2014). "A loss-of-function ARHGEF10 (ENSCAFG00000013667) deletion was identified which, although not explanatory for all Leonberger polyneuropathy, is highly-associated with a juvenile-onset form of the disease." (PMID 25275565, 2014). "The effect of the deletion on the ARHGEF10 transcript was investigated with cDNA prepared from the nervous tissue of an early-onset Leonberger PN case homozygous for the CFA16 haplotype (D/D), a CFA16 haplotype heterozygote (D/N) Leonberger with no polyneuropathy, and one control dog (N/N)." (PMID 25275565, 2014).
ischemic stroke (3 papers, 2018 to 2024). A stroke disorder caused by obstruction of blood flow to the brain, due to thrombotic (local blood clot formation) or embolic (due to a blood clot or other material traveling from another site) event. "Other downstream SNPs in ARHGEF10 are associated with the risk of ischemic stroke in East Asian populations." (PMID 35420468, 2022). "For example, rs11833579 of WNK and rs12425791 of NINJ2 have been found closely associated with Asian stroke and ischemic stroke, respectively, and ARHGEF10 gene polymorphism is closely associated with the risk of ischemic stroke in Northern Han Chinese population." (PMID 29631604, 2018). "Rho Guanine Nucleotide Exchange Factor 10 (ARHGEF10) has previously been linked to nerve conduction velocity, neuropathy, and elevated risk of ischemic stroke." (PMID 39062924, 2024).
autism (2 papers, 2018 to 2021). Persistent deficits in social interaction and communication and interaction as well as a markedly restricted repertoire of activity and interest as well as repetitive patterns of behavior. "Based on the distinctive roles of the frontal cortex and amygdala in autism, the neurochemical changes in these brain regions may be linked to the observed phenomena in Arhgef10 knockout mice." (PMID 29456827, 2018). "In addition, ARHGEF10 is included among autism genes with a suggestive evidence score in the SFARI database (score 3)." (PMID 33925474, 2021). "Although the finding of a lower level of anxiety in Arhgef10 knockout mice is inconsistent with another reported autism-like mouse strains, the reduced anxiety in Arhgef10 knockout mice indicates that social interaction defects were not caused by anxiety-like behavior." (PMID 29456827, 2018).
behavior disorders (2 papers, 2021). "Both DLGAP2 and ARHGEF10 could be potential candidates for behavioral disorders, in accordance with the phenotype of Dlgap2-/- and Arhgef10-/- mice." (PMID 33925474, 2021). "The Arhgef10-depleted mice showed mental and behavior disorders." (PMID 34238319, 2021).
colorectal cancer (2 papers, 2008 to 2023). A primary or metastatic malignant neoplasm that affects the colon or rectum. "In addition, while decreased ARHGEF10 expression was observed in tumor cells in these studies, increased ARHGEF10 expression was found in colorectal cancer in our study." (PMID 37489460, 2023).
depression (2 papers, 2016 to 2018). "The elevated serotonin levels found in the brains of Arhgef10 knockout mice correlate with attenuated depression-like behaviors observed in the FST and the TST." (PMID 29456827, 2018). "Compared with their wild-type littermates, the Arhgef10-depleted mice showed social interaction impairment, hyperactivity, and decreased depression-like and anxiety-like behavior." (PMID 29456827, 2018). "In addition, Arhgef10 knockout mice also displayed reduced anxiety-like and depression-like behaviors and increased locomotor activity." (PMID 29456827, 2018). "In addition, the elevated serotonin level in brain found in Arhgef10 knockout mice can also explain their attenuated depression-like behaviors in the FST and the TST." (PMID 29456827, 2018). "We further evaluated specific depression-like behavior using the FST and the TST, to verify that social deficits in Arhgef10 knockout mice are not caused by depression-related effects." (PMID 29456827, 2018). "On the other hand, ARHGEF10 knockout mice displayed hyperactivity in the locomotor test, reduced anxiety-like behavior in the EPM, and reduced depression-like behavior in the FST and TST." (PMID 29456827, 2018). "The lower levels of anxiety-like and depression-like behavior further demonstrated that the social traits in Arhgef10 knockout mice were not the results of mood-related behavioral abnormalities." (PMID 29456827, 2018). "Moreover, Arhgef10 knockout mice did not exhibit depression-like or anxiety-like behavior, suggesting that the social deficit was not confounded by these factors." (PMID 29456827, 2018).
developmental delay (2 papers, 2021 to 2025). "This segment contains the OMIM genes DLGAP2, CLN8, and ARHGEF10, which are considered candidate genes for developmental delay, intellectual disability and neurobehavioral disorders." (PMID 40790240, 2025).
pancreatic cancer (2 papers, 2021 to 2023). "CTNNA1 is a key component of the E-cadherin adherens junction while ARHGEF10 is a GTP exchange factor for RhoGTPases with in vitro studies demonstrating increased cell motility and invasiveness in ARHGEF10 depleted pancreatic cancer cells." (PMID 37973922, 2023).
schizophrenia (2 papers, 2021). A major psychotic disorder characterized by abnormalities in the perception or expression of reality. "ARHGEF10 variants have been also associated to schizophrenia and to Charcot-Marie Tooth disease type 1A (CMT1A)." (PMID 33925474, 2021). "Some studies have claimed that ARHGEF10 was also associated with schizophrenia." (PMID 34238319, 2021).
age-related macular degeneration (1 paper, 2012). Age-related loss of vision in the central portion of the retina (macula), secondary to retinal degeneration. "Two of these genes have been related to ophthalmologic disorders, including age related macular degeneration (HMCN1) and keratoconus (VSX1) and several have been related to neurologic disorders (IKBKAP, SGCG, SACS, ARHGEF10, and CACNA1S)." (PMID 23139751, 2012).
Anxiety (1 paper, 2018). Intense feelings of nervousness, tension, or panic often arise in response to interpersonal stresses. "Arhgef10 knockout mice spent a longer duration in the open arms than WT mice, implying reduced anxiety-like behavior in Arhgef10 knockout mice." (PMID 29456827, 2018). "The reduction of anxiety-like behavior strengthened the correlation between Arhgef10 and social behavior and suggests the involvement of Arhgef10 in anxiety-related behavior." (PMID 29456827, 2018). "It was found that Arhgef10 knockout mice displayed less anxiety-like behavior." (PMID 29456827, 2018). "The results demonstrated that there was a reduction of anxiety-like behavior in Arhgef10 KO mice." (PMID 29456827, 2018). "The reduced anxiety-like behavior and hyperactivity phenotype observed in Arhgef10 knockout mice may be a sign of increased impulsive behavior." (PMID 29456827, 2018).
Behcet disease (1 paper, 2023). A chronic, relapsing, multisystemic vasculitis characterized by mucocutaneous lesions, as well as articular, vascular, ocular and central nervous system manifestations. "The ARHGEF10 gene might be associated with the pathogenesis of Behcet’s disease." (PMID 37489460, 2023).
breast carcinoma (1 paper, 2020). "Moreover, we found that the tumor suppressor ARHGEF10 and the oncogene SRFS1 were negatively and positively co-regulated by miR-106b-5p, miR-106a-5p, miR-671-5p, and miR-590-3p, whereas this pattern was observed at the protein level in breast cancer tissues, validating our results." (PMID 32635183, 2020).
epilepsy (1 paper, 2021). A brain disorder characterized by episodes of abnormally increased neuronal discharge resulting in transient episodes of sensory or motor neurological dysfunction, or psychic dysfunction. "ARHGEF10, together with CLN8, also falls within the 123 kb deletion of patient 6 who has motor coordination problems and epilepsy." (PMID 33925474, 2021).
microcephaly (1 paper, 2021). A congenital or acquired developmental disorder in which the circumference of the head is smaller than normal for the person's age and sex. "In particular, ARHGEF10 is involved in neuronal morphogenesis and DECIPHER Patient 368323, which carries an ARHGEF10 SNV, presents microcephaly; CSMD1 and KBTBD11 are brain-specific expressed genes, and CSMD1 is also dosage-sensitive." (PMID 33925474, 2021). "The CR comprises several genes out of which the OMIM genes FBXO25, DLGAP2, CLN8, ARHGEF10 and MYOM2, most of which share a role in neural differentiation and function, are main candidates for DD/ID, microcephaly and neurobehavioral disorders." (PMID 33925474, 2021).
mood disorder (1 paper, 2018). A cognitive disorder a disturbance in which the person's mood is hypothesized to be the main underlying feature. "These behavioral changes further confirmed that the social deficits in Arhgef10 knockout mice were not confounded by mood disorders." (PMID 29456827, 2018).
neuroblastoma (1 paper, 2025). Neuroblastoma (NB) is the most common solid, extracranial childhood tumor. "To further explore a potential interaction between TRPV4 and ARHGEF10, we utilized MN-1 cells (a mouse motor neuron-neuroblastoma fusion cell line) to perform a series of cell-based studies of TRPV4-ARHGEF10 interactions." (PMID 41338459, 2025).
orofacial cleft (1 paper, 2019). A disorder of facial skeleton that is characterized by cleft lip and/or cleft palate that result in feeding, speech and hearing problems caused by failures during development. "The remaining SNPs had q-values above 0.76 and are not considered any further.ARHGEF10 has not previously been linked with orofacial clefts." (PMID 31372216, 2019). "LikeANK3,ARHGEF10 has not previously been associated with orofacial clefts, and the Hetionet results are consistent with this observation.ARHGEF10 encodes a Rho guanine nucleotide exchange factor that may be involved in neural morphogenesis." (PMID 31372216, 2019).
osteoporosis (1 paper, 2023). A condition of reduced bone mass, with decreased cortical thickness and a decrease in the number and size of the trabeculae of cancellous bone (but normal chemical composition), resulting in increased fracture incidence. "Of four key crosstalk genes (ARHGEF10, PCDH7, CST6, and ROBO3), PCDH7 was identified and validated as relating the development of both sarcopenia and osteoporosis." (PMID 37476411, 2023).
osteosarcoma (1 paper, 2009). A usually aggressive malignant bone-forming mesenchymal neoplasm, predominantly affecting adolescents and young adults. "The supernumerary centrosome phenotype was also observed in S phase-arrested osteosarcoma U2OS cells when the expression of ARHGEF10, RhoA or KIF3B was abrogated by RNA interference." (PMID 19635168, 2009). "The effect of knockdown of ARHGEF10, RhoA or KIF3B was also examined in osteosarcoma U2OS cells arrested in S phase by aphidicolin treatment." (PMID 19635168, 2009).
tumor (10 papers, 2008 to 2025). "However, transient expression of ARHGEF10 in vitro was associated with the loss of actin stress fibres and the formation of membrane filopodia, which facilitate individual tumour cell migration." (PMID 30566430, 2018). "Recent reports suggest that ARHGEF10 participates as a tumor suppressor involved in the activation of apoptosis during DNA damage." (PMID 32635183, 2020). "Loss of 8p23.3, a region affected by deletion in both breast and pancreatic cell lines targeted 10 genes including ARHGEF10, a potential tumor suppressor." (PMID 20932292, 2010). "We identified 42 and 16 TSGs monoallelically deleted in P2 and P5, respectively, including several TSGs deleted in both tumor samples (ARHGEF10, CDKN1B, ETNK1, ETV6, LEPROTL1, NRG1, PTPN6, and WRN) and many TSGs co-deleted in the same subclone as well as across multiple subclones." (PMID 38658552, 2024). "The pattern of rearrangements seen on 8p may be a consequence of the high density of potential targets on this chromosome arm, and ARHGEF10 may be a new candidate tumour suppressor gene." (PMID 18840272, 2008). "Likely due to the greater sequencing read depth, patient 1,010,020 had a substantially greater number of such genes—a total of 187; these likewise included several tumor suppressor genes, such as ANGPTL4, ARHGEF10, MARVELD1, and SQSTM1." (PMID 41428220, 2025). "ARHGEF10 belongs to the Rho guanine nucleotide exchange factor (GEF) family, which stimulates Rho GTPases and has been shown to have tumor suppressor activity and inhibits proliferation." (PMID 32349335, 2020). "Even though these results were obtained with a limited number of samples, it deserves future analysis to corroborate the correlation between the expression of ARHGEF10 and SRSF2 in a large number of tumor tissues." (PMID 32635183, 2020).
cancer (4 papers, 2008 to 2024). A tumor composed of atypical neoplastic, often pleomorphic cells that invade other tissues. "ARHGEF10 encodes the Rho guanine nucleotide exchange factor, and its role in cancer has not yet been clarified." (PMID 37489460, 2023). "These CNV regions encode nineteen known genes, and some of which have been shown to affect aging-related phenotypes such as the shortening of telomere length (ZNF208), the risk of cancer (FOXA1, LAMA5, ZNF716), and vascular and immune-related diseases (ARHGEF10, TOR2A, SH2D3C)." (PMID 29883365, 2018). "A literature survey about significant biomarkers highlighted in survival analysis revealed that GNG11, CBX2, CDKN3, ARHGEF10, CLN8, SEC61G and PTDSS1 genes present similar survival and prognostic behaviors in the specified cancers." (PMID 37489460, 2023). "Expression data for multiple cancer cell lines (not shown) suggested ARHGEF10 as a more likely target gene than CLN8, since ARHGEF10 expression was decreased by more than 50% in 83% (15/18) of lines tested." (PMID 18840272, 2008).
adenocarcinoma (2 papers, 2009). A common cancer characterized by the presence of malignant glandular cells. "In both G1/S and M phases, ARHGEF10 was localized in the centrosome in adenocarcinoma HeLa cells." (PMID 19635168, 2009).
neurodevelopmental disorder (1 paper, 2021). A behavioral and cognitive disorder with onset during the developmental period that involves impaired or aberrant development of intellectual, motor, or social functions. "Out of the 11 protein coding genes encompassing the deletion intervals of our patients, DLGAP2 and ARHGEF10 appear to be, according to their expression profile and the assessed role in neural morphogenesis, differentiation and function, bona fide candidates for neurodevelopmental disorders." (PMID 33925474, 2021).
neuromuscular disease (1 paper, 2025). "Our experiments in transiently transfected MN-1 cells revealed that neuromuscular disease-causing mutations perturb the capacity of TRPV4 to immunoprecipitate with ARHGEF10." (PMID 41338459, 2025). "Mutations in ARHGEF10 have also been associated with a form of hereditary neuromuscular disease in Leonberger and Saint Bernard dogs that includes vocal fold paresis, a characteristic feature of TRPV4-mediated neuromuscular disease in human patients." (PMID 41338459, 2025). "Dominant mutations in ARHGEF10 are associated with forms of human neuromuscular disease, as well as a form of neuromuscular disease in dogs that involves vocal fold paresis, a characteristic feature of TRPV4-mediated disease." (PMID 41338459, 2025). "Strikingly, one of these interactors, ARHGEF10, is also mutated in neuromuscular disease." (PMID 41338459, 2025). "Together, these results suggest that reduced interaction of neuromuscular disease-causing TRPV4 mutants with ARHGEF10 and the resulting loss of ARHGEF10-mediated inhibition may contribute to the increased ion channel activity characteristic of these mutant channels." (PMID 41338459, 2025). "However, the inhibitory effect of ARHGEF10 was absent in cells expressing the neuromuscular disease-causing mutants." (PMID 41338459, 2025).
ARHGEF10 also shares sentences with these, for which no sentence is quoted: neurological diseases (3 papers); neuropathy (3); psoriasis (2); Stroke (2); alcohol dependence (1); Charcot-Marie-Tooth disease type 1A (1); cleft lip (1); Encephalopathy (1); genetic disorders (1); hereditary neuromuscular disease (1); Intellectual disability (1); keratoconus (1); laryngeal paralysis (1); Neonatal respiratory distress (1); peripheral neuropathy (1); sarcopenia (1); Sensory neuropathy (1).